MISP3 (MISP family member 3)
Tractability: No criterion of Open Targets' tractability assessment is met for any kind of drug.
Gene: Protein-coding gene on chromosome 19 (14,072,108 to 14,075,062, forward strand). Ensembl gene ENSG00000141854.
Homologues: Orthologues: macaque MISP3 (94% identical), dog MISP3 (86% identical), mouse Misp3 (75% identical), guinea pig MISP3 (74% identical), rat Misp3 (70% identical), zebrafish misp3 (32% identical). Paralogues in human: MISP (32% identical).
Diseases named in the same sentence as MISP3 in open-access papers:
MISP3 is named in the same sentence as 1 disease in open-access papers, as found by Europe PMC text mining. Sharing a sentence is not in itself a finding about the gene and the disease. The quoted sentences say what the papers report.
tumor (1 paper, 2025). "p < 0.0001) 19.3-fold increase in tumor (Mean ± SEM = 3.51 ± 0.12 log2TPM) compared to normal tissue (Mean ± SEM = −0.75 ± 0.2 log2RSEM); and MISP3 mRNA exhibited a significant (Adj." (PMID 41465326, 2025).